IFNG (interferon gamma)
Diseases named in the same sentence as IFNG in open-access papers (continued):
Sharing a sentence is not in itself a finding about the gene and the disease.
pancreatic adenocarcinoma (15 papers, 2015 to 2025). "The pancreatic adenocarcinoma cell lines have very low basal MHC-I expression, but are responsive to IFNγ stimulation." (PMID 32355214, 2020). "Two CAR-T cells showed increased release of IFNγ, TNFα, IL-2 and very limited production of IL-6 after stimulated by four EpCAM positive pancreatic adenocarcinoma cells while not by hTERT–HPNE." (PMID 41417221, 2025). "We showed that, in coculture with human PBMCs, control RNF43-mutant HPAF-II pancreatic adenocarcinoma cells inhibit the stimulation of GMCSF and IFNγ production as well as CD4 and CD8 T-cell proliferation, effects that were reversed by preincubation of the HPAF-II cells with RXC004." (PMID 36922934, 2022).
parasite (15 papers, 2013 to 2025). "Overall, these results indicate that IFNγ production requires an active intracellular parasite infection but depends more critically on the host mevalonate pathway than on the parasite DOXP pathway." (PMID 41452934, 2025).
salmonellosis (15 papers, 2007 to 2025). Infections with bacteria of the genus salmonella. "For instance, a deficiency in IFNγ compromises host intestinal immunity at the cellular and humoral levels by impairing macrophage function in response to Salmonella challenge, resulting in salmonellosis and septicemia." (PMID 39206201, 2024). "On the other hand, exogenous IFNγ has been shown to protect the host against lethal salmonellosis in vivo in mice." (PMID 39206201, 2024). "The serum IFNγ, IL-12 and IL-18 levels were increased significantly in patients with both systemic and gastrointestinal form of salmonellosis." (PMID 20161765, 2010). "One key cytokine controlling bacterial infection, i.e. salmonellosis, is interferon gamma (IFN-γ)." (PMID 21829463, 2011). "Likewise, increased numbers of γδ-T cells are found in murine salmonellosis, particularly in the peritoneal cavity, and these produce IFNγ in response to Salmonella-infected macrophages." (PMID 21048923, 2010). "In salmonellosis, there is often an increase in levels of pro-inflammatory cytokines like interleukins (IL-1 and IL-6), TNF-α, and interferon-gamma (IFN-γ)." (PMID 38667028, 2024). "The higher upregulation of pro-inflammatory genes (Ifnγ, Kc, Inos, Il1β) and the higher concentration of immune proteins (MPO, KC) that we observed in SA+/ST−/mCRAMP−/− and SA+/ST+/mCRAMP−/− mice are clear indications of a higher susceptibility to salmonellosis when cathelicidin is absent." (PMID 33292444, 2020).
skin infection (15 papers, 2011 to 2025). An inflammatory process affecting the skin, caused by bacteria, viruses, parasites, or fungi. "Excess IFNγ enhances skin infection of C. auris by dampening the protective IL-17 responses and increasing dermal damage." (PMID 40294061, 2025). "Taken together, our findings suggest that IFNγ enhances skin infection of C. auris by dampening the protective IL-17 responses and increasing dermal damage." (PMID 40294061, 2025). "Therefore, we examined if IFNγ regulates fungal burden during C. auris or C. albicans skin infection." (PMID 40294061, 2025). "This could be partly due to the route of infection, as epicutaneous and intradermal infection elicits different immune responses, and future studies are required to understand the functional importance of IFNγ (Th1) in C. auris skin infection." (PMID 39536069, 2024). "For example, interferon-gamma, a cytokine that plays a role in the immune response against mycobacterial infections, has been used as an adjunct to antimicrobial therapy in some cases of NTM skin infections, particularly in patients with underlying immunosuppressive conditions." (PMID 37731736, 2023). "However, while iKIR plus IgG control decreased bacterial load, the treatment of mice with anti-IFNGR antibody did not prevent iKIR effects on bacterial clearance, demonstrating that IFNγ is not solely involved in the inhibitory effects of SOCS-1 during MRSA skin infection." (PMID 33690673, 2021).
syphilis (15 papers, 2017 to 2025). A contagious bacterial infection caused by the spirochete Treponema pallidum. "In the whole syphilis group, individuals with the AA genotype of +874 T>A polymorphism had significantly lower pretreatment serum levels of IFNγ compared with the TA+TT genotypes." (PMID 40529360, 2025). "Patients with serofast syphilis had significantly lower baseline levels of serum IFNγ compared with individuals from the serologically-cured group." (PMID 40529360, 2025). "In the immunological milieu of early syphilis, a significant upregulation of interferon-gamma (IFN-γ) is noted in the plasma, accompanied by a propensity of Th cells to differentiate towards the Th1 phenotype." (PMID 38694502, 2024). "A diagnosis of syphilis in humans and animal models is typically characterized by elevations in both plasma pro-inflammatory (TNFα, IFNγ, CCL4, IP-10) and anti-inflammatory cytokines (IL-10)." (PMID 30253745, 2018). "Our ex vivo studies demonstrate the importance of CD64-potentiated uptake of opsonized Tp and suggest that IFNγ-activated macrophages have an important role in the context of early syphilis." (PMID 29051759, 2017). "We prospectively recruited all patients with a new diagnosis of syphilis and tested their plasma for IFNα, IFNγ, IL-1β, IL-12p40, IL-12p70, IP-10, MCP-1, MIP-1α, MIP-1β, IL-4, IL-5, IL-6, IL-7, IL-8, IL-10 and IL-17A at baseline pre-treatment and 6 months following therapy." (PMID 28143443, 2017). "The following tests can rule out the main differential diagnosis: syphilis serology, ACE level, Interferon gamma release assay, and chest X-ray." (PMID 36013011, 2022).
Zinc deficiency (15 papers, 2009 to 2026). A deficiency of the essential metal Zinc; an essential cofactor for many enzymes. "In humans, Zinc deficiency has been reported to cause an imbalance between Th1 and Th2 cells: the Th1 function is decreased, while Th2 function is not affected, with increase in the production of IFNγ, IL-2, and tumour necrosis factor α (TNFα)." (PMID 27143960, 2016).
adult-onset immunodeficiency syndrome (14 papers, 2019 to 2025). "Adult-onset immunodeficiency syndrome (AOID) patients with autoantibodies (autoAbs) against interferon-gamma (IFN-γ) generally suffer from recurrent and recalcitrant disseminated non-tuberculous mycobacterial diseases." (PMID 34072539, 2021).
astrocytoma (14 papers, 2012 to 2025). "It has been reported that IFNγ treatment can modulate the expression of BAF155/SMARCC1 in human astrocytoma cell lines." (PMID 33809795, 2021). "In light of the finding that chronic inflammation is an important histopathologic feature in AD, recent studies have revealed that the stimulation of human primary astrocytes or the astrocytoma cell line U373 with IFNγ and TNFα or IFNγ and IL-1β triggered the production of Aβ1–40 and Aβ1–42." (PMID 29707568, 2018). "Moreover, in rat C6 astrocytoma cells, Lib was observed to be upregulated in response to pro‐inflammatory cytokines, including tumor necrosis factor‐α (TNF‐α), interleukin‐1 beta (IL‐1β), and interferon gamma (IFN‐γ)." (PMID 40642947, 2025).
bone marrow failure (14 papers, 2014 to 2026). "Interferon-gamma (IFN-γ) is a central mediator of immune-driven bone marrow failure (BMF) in acquired aplastic anemia (AA)." (PMID 41811900, 2026). "In summary, platelets regulate the immune responses of CD4+ and CD8+ T cells through mitochondrial energy metabolism, contributing to immune dysregulation and increased levels of IFNγ and TNFα, leading to the destruction of HSPCs and potential bone marrow failure." (PMID 40552264, 2025). "Given that IFNγ can impair hematopoietic stem cell function and contribute to bone marrow failure, it is possible that the presence of these activated T cells in marrow may directly participate in disruption of marrow function in advanced stage disease." (PMID 33996605, 2021). "Key cytokines including interferon-gamma (IFN-γ) and tumor necrosis factor-alpha (TNF-α) play crucial roles in this immune dysregulation, influencing HSPCs and contributing to bone marrow failure." (PMID 40552264, 2025).
dilated cardiomyopathy (14 papers, 2012 to 2025). Cardiomyopathy which is characterized by dilation and contractile dysfunction of the left and right ventricles. "In support of this, high levels of plasma IFNγ, TNFα, (IL-1β), and IL-6 correlated with the severity of dilated cardiomyopathy in chagasic patients, indicating that exacerbated immune can cause local damage." (PMID 29867974, 2018). "Others used cardiac tissue from CCC and dilated cardiomyopathy patients in a gene expression profiling assay to suggest that chemokine signaling and interferon gamma (IFN-γ) in human cardiomyocyte could upregulate genes involved in Chagasic hypertrophy." (PMID 26771187, 2016).
endometrial cancer (14 papers, 2017 to 2025). Primary or metastatic malignant neoplasm involving the endometrium (mucous membrane that lines the endometrial cavity). "In endometrial cancer, HLA-DMB expression was primarily associated with wound healing, interferon-gamma dominant, inflammatory, and lymphocyte-depleted molecular subtypes, but less so with immunologically quiet and transforming growth factor-beta dominant subtypes." (PMID 39917362, 2024). "More importantly, presence of IFNγ-pathway mutations did not result in significantly higher overall mortality in cancer types with the highest mutational frequency, and even correlated with improved survival in endometrial cancer." (PMID 39746898, 2025). "Endometrial cancer cell lines with JAK1 frameshifts have been shown to be resistant to the effects of IFNγ, including a lack of growth arrest and a failure to up regulate antigen processing and presentation." (PMID 29121062, 2017).
enteropathy (14 papers, 2011 to 2025). "In a cohort study of 29 CVID patients presenting with non-infectious disease complications, plasma protein profiling demonstrated that plasma type 1 cytokine levels (IL-12/IFNγ) were associated with more severe disease outcomes which included enteropathy." (PMID 38803492, 2024). "Consequently, CXCL10 showed a strong correlation with IFNγ expression in the intestinal mucosa in normal tissues and in severe enteropathy." (PMID 24586509, 2014). "Enteropathy secondary to olmesartan therapy results from the drug’s ability to induce T-cell activation and dysregulate cytokines, including tumor necrosis factor alpha (TNF-α) and interferon gamma (IFN-γ)." (PMID 40724600, 2025).
hypothyroidism (14 papers, 2009 to 2025). Abnormally low levels of thyroid hormone. "When crossed to LMP2 deficient mice, the thyr-IFNγ double mutant mice corrected the hypothyroidism (sixth group) and restored a normal body weight in both males and females." (PMID 19924240, 2009). "In addition, IL-12, which controls IFNγ and T-bet expression in activated T cells, is another miR-29a target that has been linked to hypothyroidism in AITD." (PMID 29881372, 2018). "The results indicate that LMP2 is involved not only in oncocyte formation but also in the development of hypothyroidism and growth defect initiated by IFNγ." (PMID 19924240, 2009).
Kawasaki disease (14 papers, 2015 to 2024). A rare inflammatory disease characterized by an acute febrile, systemic, self-limiting, medium-vessel vasculitis primarily affecting children. "In particular, the rs1861493 SNP (T/C) on the IFNG gene has been described to be in LD with rs1861494 SNP, and it is associated with some diseases, like Kawasaki Disease, in which IFNG production plays an important role in its immunopathogenesis." (PMID 29361774, 2018). "IFNG gene encoding interferon (IFN)-γ, produced by natural killer cells and T cells, has been suggested to play an important role in the immunopathogenesis of Kawasaki disease." (PMID 27124053, 2016).
mammary adenocarcinoma (14 papers, 2017 to 2025). "VSV encoding IFNγ (VSVΔ51VSVΔ51-IFNγ) was used for the treatment of 4T1 mammary adenocarcinoma as well as CT26 colorectal murine tumours." (PMID 36140243, 2022). "In the in vivo study, increasing of metastatic potential was also attributed to the increased resistance to NK cells in IFNγ gene-transfected TS/A mammary adenocarcinoma cells." (PMID 33579265, 2021).
myelodysplastic syndrome (14 papers, 2012 to 2025). A clonal hematopoietic disorder characterized by dysplasia and ineffective hematopoiesis in one or more of the hematopoietic cell lines. "Paradoxically, Setd2 loss conferred resistance to IFNγ-induced HSPCs exhaustion, which may contribute to the maintenance of Setd2-deficient HSPCs in our myelodysplastic syndrome (MDS) model under the inflammatory milieu." (PMID 41198622, 2025). "The efficacy of CD33/CD16 BiKE to induce NK cell function in myelodysplastic syndrome (MDS) cases showed significant NK cell degranulation and IFNγ and TNFα production in MDS patients." (PMID 34827170, 2021).
pneumococcal meningitis (14 papers, 2012 to 2025). An acute purulent infection of the meninges and subarachnoid space caused by Streptococcus pneumoniae, most prevalent in children and adults over the age of 60. "One study showed an association between IFNγ-driven acute brain pathology and the long-term neurological sequelae resulting from pneumococcal meningitis using IFNγ knockout mice infected by a serotype 3 strain (WU2)." (PMID 27009189, 2016). "In addition, interferon-gamma (IFNγ), a pro-inflammatory cytokine, has been demonstrated to be a key player in the pathogenesis of experimental pneumococcal meningitis." (PMID 36769171, 2023).
Rotavirus infection (14 papers, 2006 to 2025). Infection with any of the rotaviruses. "Then, we applied the same model of rotavirus infection to mice deficient in IFNγ due to a mutation in the IFNγ gene." (PMID 16623951, 2006). "Human rotavirus infection has been shown to stimulate the release of IL-1β, IL-2, IL-4, IL-6, IL-8, IL-10, IL-12, interferon-gamma (IFN-γ), and TNF-α." (PMID 36976000, 2023). "Regarding the mechanism of action of probiotics on rotavirus diarrhea, cellular experiments have demonstrated that probiotics can increase the production of interferon gamma (IFN-γ) in cells in response to rotavirus infection, and they also increased the expression of the CXCL10 gene." (PMID 35360101, 2022).
silicosis (14 papers, 2006 to 2025). Silicosis is a respiratory disease caused by breathing in (inhaling) silica dust. "Previous research demonstrated that T-helper (Th) 1 type inflammation exists in the early stage of silicosis, which is characterized by increased levels of tumor necrosis factor alpha (TNF-α) and interferon gamma (IFN-γ)." (PMID 34149803, 2021). "In this study, the level of IFNγ was higher in exposed vs. non-exposed groups and very low in the four cases of silicosis, suggesting a variation of the expression of this cytokine during the evolution of the disease." (PMID 40027509, 2025).
uveal melanoma (14 papers, 2012 to 2025). A melanoma derived from melanocytes of the uveal tract. "CAR was functional and specific because the CAR-TILs (but not mock-transfected TILs) from patient MM1 degranulated, released, and caused accumulation of interferon gamma (IFN-γ) in the medium when co-cultured with the HER2 positive uveal melanoma cell line 92-1." (PMID 36765608, 2023). "It is intriguing that even though uveal melanomas and other cancers have similar IFNγ‐induced immunological profiles, there is an opposing correlation with clinical outcome." (PMID 31025552, 2019). "In conclusion, the IFNγ/STAT1‐IRF1 signature as a component of the immune response in uveal melanomas has been validated in vivo." (PMID 31025552, 2019). "Gene expression analysis divided uveal melanomas into two groups, according to the IFNγ/STAT1‐IRF1 pathway activation." (PMID 31025552, 2019). "Although CD8+ T cells within primary UM appear to proliferate poorly, they still accumulate within primary uveal melanomas and indirect evidence suggests that they produce IFNγ." (PMID 23060881, 2012). "Interferon gamma (IFN-γ) is also highly expressed in aqueous humor of patients with uveal melanoma." (PMID 33317028, 2020). "IFNγ may actually promote immune evasion by ocular tumors as primary uveal melanoma lines treated with IFNγ expressed PD-L1 which inhibited T cell function in vitro." (PMID 23060881, 2012). "Similarly, IFNγ rendered uveal melanoma cell lines resistant to lysis by CD8+ T cells." (PMID 23060881, 2012).
abscess (13 papers, 2009 to 2023). An inflammatory process characterized by the accumulation of pus within a newly formed tissue cavity which is the result of a bacterial, fungal, or parasitic infection or the presence of a foreign body. "Recent work has also demonstrated a novel role for IFNγ in the activation of the fibrinolytic system to control abscess thickness, improve leukocyte recruitment, and drive abscess breakdown during S. aureus and C. albicans infection." (PMID 33690673, 2021). "Interestingly, SOCS-1 inhibition mimicked several aspects of the protective effects of IFNγ such as a highly organized and compact abscess with a thick capsule." (PMID 33690673, 2021). "Mice in the IFNγ + CLP group showed only mild shortness of breath, decreased activity, lethargy, decreased intraperitoneal exudation, presence of small abscesses formed by adhesion of the caecal ligation site, and only a mild dilation of the intestinal tract." (PMID 37434129, 2023). "No participant with an abscess had a positive interferon-gamma release assay." (PMID 35031617, 2022).
allergic contact dermatitis (13 papers, 2009 to 2024). An inflammatory skin condition caused by an immune response to direct contact between the skin and an allergen. "In particular, glutathione may suppress the immune reaction in mice with allergic contact dermatitis, inhibit the production of inflammatory cytokines, and maintain the adequate production of interferon-gamma by dendritic cells." (PMID 37374099, 2023). "In the model of CD8+ T cell-mediated skin inflammation, which reproduces allergic contact dermatitis in human, inhibition of skin inflammation by L. casei is not due to impaired priming of hapten-specific IFNγ-producing cytolytic CD8+ effector T cells." (PMID 19300508, 2009).
amebiasis (13 papers, 2011 to 2026). A parasitic infectious disorder caused by amoebas. "For instance, the association of stool IgA and PBMC IFNγ with protection from amebiasis in humans informed the weighting factors of the immunological readouts employed in the DOE and desirability index analysis here." (PMID 34248966, 2021). "Encouragingly, protection from amebiasis in humans has been associated with mucosal IgA and IFNγ production from PBMCs; in addition, IL-17A production from splenocytes was associated with protection in a mouse challenge model." (PMID 34248966, 2021). "In the murine model of hepatic amebiasis, which mirrors the sex‐related differences observed in humans, splenocytes from female mice produced higher levels of IFNγ." (PMID 41546136, 2026). "Interferon-gamma (IFN-γ) is secreted along with Th1 responses toward intestinal amebiasis and was shown to play a protective role by clearing the amebae." (PMID 39931329, 2024). "Amebiasis is marked by acute inflammation with the release of cytokines (tumor necrosis factor alpha (TNFα), interleukin 8 (IL-8), IL-1β, interferon gamma (IFN-γ), reactive oxygen species (ROS), and nitric oxide (NO) from activated cells of the immune system." (PMID 30308066, 2018). "Cell-mediated interferon gamma (IFN-γ) appears to provide protection from amebiasis through its ability to activate neutrophils and macrophages to kill the parasite." (PMID 23990778, 2013).
chronic hepatitis (13 papers, 2009 to 2025). An active inflammatory process affecting the liver for more than six months. "WHV-specific CTLs were more robustly augmented by anti-PD-1 than by anti-PD-L1 in chronic hepatitis, while global IFNγ-positive CTL response was significantly suppressed in chronic hepatitis compared to persistent occult infection." (PMID 36560951, 2022).